RN7SL337P (RNA, 7SL, cytoplasmic 337, pseudogene)
Gene: Miscellaneous RNA gene on chromosome 19 (14,584,095 to 14,584,395, forward strand). Ensembl gene ENSG00000243488.
Homologues: Orthologues: chimpanzee Metazoa_SRP (98% identical), macaque Metazoa_SRP (92% identical). Paralogues in human: RN7SL842P (94% identical), RN7SL1 (81% identical), RN7SL2 (80% identical), RN7SL3 (80% identical), RN7SL296P (78% identical), RN7SL126P (78% identical), RN7SL230P (78% identical), RN7SL14P (78% identical), RN7SL566P (78% identical), RN7SL122P (77% identical), RN7SL664P (76% identical), RN7SL118P (76% identical), and 701 more.